ENO1 (enolase 1)
Diseases named in the same sentence as ENO1 in open-access papers (continued):
Sharing a sentence is not in itself a finding about the gene and the disease.
glioma (continued). "Survival analyses conducted on TCGA and CGGA datasets revealed that high ENO1 expression correlated with poor prognosis in GBM patients and was significantly upregulated in recurrent gliomas, suggesting its potential as an independent prognostic biomarker." (PMID 41353343, 2025). "The expression of enolase 1 (ENO1) and hexokinase 2 (HK2) has been shown to play an important role in the occurrence and metastasis of glioma cells." (PMID 37627013, 2023). "In glioma, high SNHG18 expression enhances radiation resistance, and triggers EMT by increasing ENO1 expression." (PMID 33028341, 2020). "Knockdown of ENO1 expression decreases the cell growth, migration, and progression of invasion via the inactivation of the PI3K/Akt pathway in glioma cells." (PMID 32013122, 2020). "We screened two potential partner proteins, ENO1 and Homer3, that showed high coverage with WBP2; their corresponding genes are vital in the development of glioma and the nervous system, respectively." (PMID 29497031, 2018). "Previous research has indicated that ENO1 can positively affect the PI3K/Akt signaling pathway, promoting cell growth and migration in glioma cell." (PMID 29497031, 2018). "We found that forced expression of WBP2 promoted, while limited expression of WBP2 inhibited, ENO1 expression and its downstream PI3K/Akt signaling pathway in glioma cells." (PMID 29497031, 2018). "In short, our findings illustrate that WBP2 modulates the expression and activity of ENO1 and further mediates EMP pathway activity through the PI3K/Akt signaling pathway, to regulate the biologic behavior of glioma cells." (PMID 29497031, 2018). "We found that the transcription of ENO1 was upregulated in the EGFP-WBP2 group and downregulated in the WBP2-silenced glioma cells." (PMID 29497031, 2018). "We also revealed how WBP2 promotes cell proliferation and regulates the cell cycle by modulating ENO1 activity and the ENO1-PI3K/Akt signaling pathway by binding to ENO1 and Homer3 in glioma cells." (PMID 29497031, 2018). "We selected seven glycolytic genes (HK2, PFKP, ALDOA, PGAM1, ENO1, ENO2 and PDK1) and confirmed their strong up-regulation under hypoxia by QPCR in seven GBM cell lines (five patient derived glioma stem-like cells and two adherent GBM cell lines)." (PMID 25932951, 2015). "We provide compelling evidence that attenuated ENO1 expression leads to suppressed cell growth, migration and invasion progression by inactivating the PI3K/Akt pathway in glioma cells." (PMID 24650096, 2014). "Knockdown of ENO1 expression led to suppressed cell growth, migration and invasion progression by inactivating the PI3K/Akt pathway in glioma cells." (PMID 24650096, 2014). "Treatment of glioma U251 and U87 cells with LY294002 had a similar effect on E-Cadherin, Cyclin D1, and p-Rb as ENO1 knockdown." (PMID 24650096, 2014). "Among these, ENO1 was identified as the most significantly downregulated protein in the secretomes of both TMZ-shATG5 and TMZR-shATG5 cells, and its function had not been previously explored in the extracellular environment of gliomas." (PMID 41353343, 2025). "Together, these data suggest that at least for ENO1-deleted gliomas, tumors in vivo—unlike cells in culture—show limited dependence on glutaminolysis and instead primarily depend on glycolysis for anaplerosis." (PMID 34172075, 2021). "To determine whether SNHG18's glioma cell motility promotion ability involves ENO1, we utilized SNHG18 overexpressed glioma U251 cells with simultaneous suppression of ENO1 using a specific siRNA, siENO1." (PMID 31798634, 2019). "Therefore, our data confirm that interactions between ENO1, Homer3, and WBP2 potentially mediate the cancer-promoting effects initiated by upregulation of WBP2 in glioma cells." (PMID 29497031, 2018). "However, the cross-talk between ENO1, Homer3, and WBP2 remains poorly understood in the progression of glioma." (PMID 29497031, 2018).
glioma (continued). "Unlike established Enolase inhibitors, ENOblock does not show selective toxicity to ENO1-deleted glioma cells in culture." (PMID 28030597, 2016). "Furthermore, we observed that decreased ENO1 expression suppressed p-PI3K and p-AKT protein levels in EC, which was consistent with our findings in glioma." (PMID 25951350, 2015). "We found that suppressed ENO1 significantly decreased the protein levels of β-catenin and phosphorylated PI3K and AKT, but not their total protein levels in SPCA-1 cells, which is similar to our previous report in glioma." (PMID 25887760, 2015). "The exact mechanisms by which ENO1 expression is mediated and its function in glioma are not well understood currently." (PMID 24650096, 2014). "Glutaminolysis, but not glycolysis, is reduced in Plasmax-cultured ENO1-deleted glioma cells corresponding to the absence of in vivo efficacy of glutaminolysis inhibitor CB-839.In standard DMEM medium, cells with and without ENO1 deletion were equally sensitive to CB-839 treatment." (PMID 39355125, 2024). "In the current study, we found that glioma cell lines that have either homozygous (D423) or heterozygous (D502, U343) deletions of ENO1 are selectively more sensitive to the enolase inhibitor POMHEX than are ENO1 rescued (D423 ENO1) and wild-type cells (LN319)." (PMID 34172075, 2021). "Thus, we argue that bioenergetic collapse, together with reduced pyruvate flux to the TCA cycle, accounts for the dramatic antineoplastic efficacy of HEX against ENO1-deleted gliomas and that glutamine oxidation may not be obligatory for tumor sustenance in vivo." (PMID 34172075, 2021). "We found that omission of exogenous pyruvate in DMEM significantly sensitized all glioma cell lines to the enolase inhibitor POMHEX, irrespective of ENO1 status." (PMID 34172075, 2021). "Indeed, we also observed that the toxicity of CB-839 in ENO1-deleted cells is significantly attenuated in physiological PlasmaxTM medium compared to DMEM medium, which implies that in vivo tumor microenvironment may not be conducive to glutamine addiction, at least for ENO1-deleted gliomas." (PMID 34172075, 2021). "For example, the binding sites of SNHG18 and ENO1 were not identified, and the upstream mechanism regulating SNHG18 expression in glioma is unclear." (PMID 31798634, 2019). "Moreover, rather than altering ENO1 expression, SNHG18 suppressed its nucleocytoplasmic transport by directly combining with ENO1 in glioma cells." (PMID 31798634, 2019).
gastric cancer (51 papers, 2012 to 2025). A primary or metastatic malignant neoplasm involving the stomach. "In gastric cancer, elevated ENO1 expression is significantly associated with Lauren classification, lymph node metastasis, and TNM stage." (PMID 40365984, 2025). "Despite the valuable insights this study provides regarding the prognostic significance and association between ALDOA and ENO1 in gastric cancer, it has several limitations." (PMID 41049005, 2025). "In several malignancies, i.e., bladder, breast, colorectal, lung, and gastric cancer, the ENO1 expression was associated with a worse prognosis." (PMID 39194522, 2024). "The overexpression of ENO-1 is associated with disease progression, metastasis-free survival, and overall survival in colorectal cancer, BC, gastric cancer, gliomas, head and neck cancer, and leukemia." (PMID 36768924, 2023). "The oncogenic potential of ENO1 was supported in human gastric cancer tissues, in which higher ENO1 expression associated with shorter overall survival." (PMID 37779896, 2023). "Our group previously observed that the transfection of gastric cancer cells with cagA could cause high expression of ENO1." (PMID 36295613, 2022). "In the CGS and PCD stages, H. pylori may accelerate the pathogenic progression toward the precancerous and cancerous lesions by up-regulating ENO1 expression, and thus increase the risk of gastric cancer." (PMID 36295613, 2022). "Finally, the elevated levels of ENO1 proteins were associated with the shorter overall survival of gastric cancer patients." (PMID 28548950, 2017). "Moreover, in gastric cancer, ENO1 protein levels are associated with chemoresistance." (PMID 33628097, 2021). "In gastric cancer, ENO1 promotes tumor growth 45 by stabilizing the expression of genes such as SOX9, VEGF-α, GPRC5A, and MCL-1." (PMID 40303285, 2025). "ENO1 is a key glycolytic enzyme and is upregulated in multiple human cancers, including ovarian cancer, hepatocellular carcinoma, and gastric cancer." (PMID 37016705, 2023). "In previous studies, we have confirmed that CCDC65 mediated the ubiquitination degradation of ENO1 by recruiting FBXW7 in gastric cancer." (PMID 35844805, 2022). "ENO1 is overexpressed in a variety of GI tumors, including colon, pancreatic, and gastric cancers, and promotes tumor development." (PMID 35602603, 2022). "It was observed that up-regulated ENO1 expression in gastric cancer cells co-cultivated with H. pylori." (PMID 36295613, 2022). "In the cultured gastric cancer cells the H. pylori-infected group had significantly enhanced ENO1 expression compared with the uninfected control group." (PMID 36295613, 2022). "Among phenylpropanoids, salidroside can inhibit the activities of multiple enzymes PKM2, GLUT1, and ENO1 in gastric cancer cells." (PMID 36438836, 2022). "Another article also demonstrated that, in gastric cancer, knockdown of ENO1 led to the arrest of the cell cycle at the G1 phase and promoted the apoptosis of MKN-45 and MGC-803 cells." (PMID 35434271, 2022). "In previous studies, we have confirmed that CCDC65 only downregulated the protein levels of ENO1 in gastric cancer." (PMID 35844805, 2022). "It has been shown that inhibition of ENO1 with shRNA inhibitor is an effective method for freezing the development of gastric cancer." (PMID 34659659, 2021). "Studies have shown that ENO1 as a glycolytic protein is also a cancer marker for malignancies such as head, neck, and gastric cancers." (PMID 34659659, 2021). "CPT1A can promote the proliferation of breast cancer cells by succinylation of enolase 1 and enhance metastasis of gastric cancer (GC) cells by succinylation of S100A10." (PMID 33681201, 2021). "In similar fashion, ENO1 is linked to the AKT signaling pathway, is involved in promoting gastric cancer cell proliferation and metastasis and serves as a potential biomarker for certain cancers." (PMID 33050649, 2020).
gastric cancer (continued). "Previous studies have shown that down-regulation of ENO1 can increase the sensitivity of cisplatin in gastric cancer cells." (PMID 30301274, 2018). "ENO1 serves as a master regulator of tumor glycolysis and predicts an unfavorable prognosis for gastric cancers." (PMID 28548950, 2017). "By proteomic screening, we found the increased expression of the glycolytic enzyme Enolase 1 (ENO1) in cisplatin-resistant gastric cancer cells." (PMID 28548950, 2017). "In conclusion, the increased ENO1 expression enhanced glycolysis in drug-resistant gastric cancer cells." (PMID 28548950, 2017). "In conclusion, ENO1 is a novel biomarker to predict drug resistance and overall prognosis in gastric cancer." (PMID 28548950, 2017). "Taken together, these results suggested that miR-22 was responsible for the overexpression of ENO1 protein and glycolysis enhancement in drug-resistant gastric cancer cells." (PMID 28548950, 2017). "Consistently, we indeed found that high ENO1 expression predicted shorter overall survival of gastric cancers." (PMID 28548950, 2017). "Based on proteomic analysis of gastric cancer cells, ENO1 is an essential component of a protein–protein interaction network involved in tumor growth and metastasis; thus, silencing of ENO1 led to cell cycle arrest and growth inhibition of gastric cancer cells." (PMID 38017510, 2023). "In another study, glycolytic enzyme enolase 1 (ENO1), and in turn glycolysis, were increased in cisplatin resistant gastric cancer cells, which could be targeted by the glucose analog 2-DG." (PMID 37779896, 2023). "Cisplatin-resistant gastric cancer cells also exhibit enhanced glycolysis by upregulating ENO-1." (PMID 36768924, 2023). "However, ENO1 has been found to increase the stemness of gastric cancer stem cells by enhancing glycolysis." (PMID 36476328, 2022). "The present study observed that the overexpressed ENO1 was mainly located at the cytoplasm and membrane of the gastric cancer cells, suggesting ENO1 might participate in aerobic glycolysis and promote gastric carcinoma proliferation, invasion and metastasis." (PMID 36295613, 2022). "Previous research reported that CCDC65 promoted ENO1 ubiquitination in gastric cancer." (PMID 35844805, 2022). "In addition, ENO1 promotes the plasminogen activation system and upregulates integrin to enhance the migration and invasion of cancers 46-48; ENO1 regulates gastric cancer cells stemness by stimulating glycolysis." (PMID 35844805, 2022). "Furthermore, the knockdown of ENO1 has been shown to promote apoptosis and induce the arrest of cell cycle in gastric cancer cells." (PMID 33643901, 2020). "Targeting ENO1 suppresses the proliferation and growth of gastric cancer cells." (PMID 31431517, 2019). "We next explored the clinical relevance of ENO1 in gastric cancer patients." (PMID 28548950, 2017). "Therefore, the stimulation of drug resistance by increased ENO1 expression in gastric cancer was most likely attributed to its enzyme activity to regulate glycolysis rather than its function as a transcription regulator." (PMID 28548950, 2017). "This study demonstrated the role of the glycolytic enzyme alpha-enolase (ENO1) in glycolysis and stemness in gastric cancer (GC)." (PMID 41168198, 2025). "Also, silencing of ENO1 resulted in and cell cycle arrest of gastric cancer cells." (PMID 24504108, 2014). "Enolase 1 (ENO1) catalyzes the conversion of 2-phosphoglycerate to phosphoenolpyruvate and is highly expressed in gastric cancer, enhancing glycolytic flux and contributing to chemoresistance." (PMID 41220952, 2025). "For instance, salidroside, a component from Rhodiola rosea, inhibits glycolysis by downregulating the expression of ENO1, PKM2, and GLUT1, leading to the induction of apoptosis in gastric cancer cells." (PMID 41220952, 2025).
gastric cancer (continued). "Following treatment with salidroside at 80 μM (at this dose, the cell viability is more than 60%), the levels of PKM2, GLUT1, and enolase 1 (ENO1) in SGC-7901 and MKN-45 gastric cancer cells decrease markedly, and glycolysis is inhibited." (PMID 36438836, 2022). "Nonetheless, we found that the mRNA levels of ENO1 and c-Myc were downregulated after the overexpression of CCDC65 in LUAD, which was different from CCDC65 in gastric cancer." (PMID 35844805, 2022). "Consistently, it has been found that hypoxia-related genes CA9, NDRG1, SLC2A1, P4HA1 and ENO1 induced EMT in hepatocellular carcinoma, bladder cancer, laryngeal cancer and gastric cancer, respectively." (PMID 34136390, 2021). "Similarly, enolase 1 (ENO1), a glycolytic enzyme, is found to be upregulated in gastric cancer (GC) cells and is associated with poor prognosis in GC patients." (PMID 34439758, 2021). "Regarding the gastric cancer cell line BGC-823, the Pkm, Pfkl, Ldha, Eno1, and Pgam2 mRNA expression levels were significantly elevated in the NE treatment group." (PMID 33855088, 2021). "Enolase 1 (ENO1) and cathepsin B (CTSB), found in both LUSC-PGS and GBM-PGS, are predictive biomarkers for hepatocellular carcinoma, gastric cancer, or oral squamous cell carcinoma." (PMID 33277589, 2020). "Therefore, miR-22 could be valuable to target ENO1 to overcome drug resistance in gastric cancers." (PMID 28548950, 2017). "Due to the unusually high expression of ALDOA and ENO1 in gastric cancer (GC) tissues, we sought to differentiate GC tissues from normal tissues based on their expression levels." (PMID 41049005, 2025). "Moreover, ENO1 regulates the AKT signaling pathway, which is essential for promoting gastric cancer cell proliferation and migration." (PMID 40365984, 2025). "Moreover, the difference in ENO1 between the H. pylori+ and the H. pylori- groups among the CSG cases was much greater than that among the PCD cases or the gastric cancer cases." (PMID 36295613, 2022). "Unexpectedly, no significantly differential expression of ENO1 was detected in the cancerous tissues between the H. pylori-positive group and the negative group of the gastric carcinoma cases." (PMID 36295613, 2022). "Clinicopathological characteristics, ENO1 and HSPB1 expression in gastric cancer samples." (PMID 22860099, 2012). "Hence, the inhibition of ENO1 by a unique small molecule inhibitor AP-III-a4 (ENOblock) could reduce the migration and invasion abilities of tumor cells in gastric cancer." (PMID 36614179, 2023). "ENO1 could regulate NSCLC and gastric cancer by regulating the cell cycle." (PMID 34504528, 2021).